AFP (alpha fetoprotein)
Diseases named in the same sentence as AFP in open-access papers (continued):
Sharing a sentence is not in itself a finding about the gene and the disease.
tumor (continued). "In conclusion, our study developed and validated a dynamic nomogram including BCLC staging, treatment modality, tumour size, and three laboratory parameters (ɣ-GGT, AFP and CRP), to predict the occurrence of MVI in patients with unresectable HCC." (PMID 35399712, 2022). "On univariate analysis, PMI, SMI, AFP level, Child-Pugh class, ALBI grade, number of tumours, maximum tumour diameter, portal vein thrombus and metastasis were all found to be associated with OS." (PMID 35639492, 2022). "Complete response and reduction in serum AFP levels were only observed in the DSMs-TACE group in our study, along with significantly better reduction in viable and total tumor diameters in the DSMs-TACE group after a median 1 (range 1 to 2) session." (PMID 35434518, 2022). "Furthermore, we could find that major tumor size and log AFP had the largest degree of separation." (PMID 36186899, 2022). "According to the variables of multiple factors, the indicators included in nomogram are BCLC staging, treatment, tumour size, ɣ-GGT, AFP and CRP." (PMID 35399712, 2022). "Expectedly, the levels of the Serum tumor marker PIVKA-II, liver tumor marker AFP and oxidation stress enzymes (GSH and MDA) significantly increased upon HCC induction." (PMID 36139719, 2022). "In contrast, markedly elevated tumor markers before TAE, such as AFP and PIVKA-II, were remedied after TAE." (PMID 35317819, 2022). "Among these genes, AFP and VEGFD are well-known tumor biomarkers that have been extensively applied in the early screening of tumors." (PMID 35719915, 2022). "In this study, we excluded the male and female-specific tumor markers (β-HCG, PSA, and free-PSA) and HGH, and only retained AFP, CEA, CA125, CA153, CA199, CA242, FER, and NSE." (PMID 35611170, 2022). "Studies have demonstrated that serum AFP levels in HCC patients were elevated with disease progression and correlated with tumor size, the sensitivity and specificity of AFP for early detection of HCC were 45.3–62% and 87–93%, respectively." (PMID 36100887, 2022). "HCV infection, albumin–bilirubin (ALBI) grade, macrovascular invasion, hand–foot skin reaction (HFSR) and baseline AFP were independent prognostic factors in patients treated with regorafenib." (PMID 36358825, 2022). "The available variables that were entered for analysis are age at diagnosis, age, gender, AFP, vascular invasion, stroma tumor ratio (STR), tumor-infiltrating lymphocyte (TIL), grade, and Stage AJCC." (PMID 35352293, 2022). "AFP has increasingly been found to serve as a predictor of HCC-related liver transplant patient survival, HCC tumor recurrence, and waitlist drop out." (PMID 36290870, 2022). "Its expression level was associated with various clinicopathological characteristics, particularly tumor size, vessel invasion, TNM stage, BCLC stage, and AFP level." (PMID 36011395, 2022). "This study also suggested that tumor size, periportal HCC and AFP ≥ 400 were independent prognostic factors for tumor progression after RFA." (PMID 34983650, 2022). "Polyembryoma, a very rare tumor in teenagers, is a mixed germ cell tumor, which secretes beta-HCG and AFP." (PMID 36553112, 2022). "In summary, AFP has been acknowledged in the diagnosis of HCC as the first and most extensively utilized tumor marker of HCC." (PMID 35624643, 2022). "Due to the clinical relevance in cancer patients, we pooled available data for different clinicopathological characteristics, including alpha-fetoprotein (AFP) levels, patient age, patient gender, vascular invasion, metastasis, tumor number and tumor size." (PMID 35884516, 2022). "For the random forest on the marginal distributions, we include tumor dose, tumor size GTV, and pre‐treatment AFP in the efficacy model, and liver dose, pre‐treatment ALBI, tumor size GTV, and prior liver directed therapy in the toxicity model." (PMID 35343595, 2022).
tumor (continued). "The other variables attaining tumor-related factors, hepatic reserve, and clinical parameters related to the severity of HIV infection were similarly distributed in patients with AFP ≥28 or <28 ng/mL." (PMID 35186078, 2022). "Later on, we assessed the association between the TCRβ CDR3 features and HCC clinical characteristics, including tumor size, microvascular invasion (MVI), and the AFP concentration in the blood." (PMID 35371059, 2022). "Four weeks after tumor implantation, animals were divided into treatment groups to receive a single intravenous injection of fLuc NPs, CpGf-CMV-sr39 NPs, or CpGf-AFP-NPs." (PMID 35857843, 2022). "In this series, combination with the serum tumor marker levels may improve the diagnostic accuracy of PET/CT of multiple primary cancers, particularly for a number of suspected tumor patients with other highly specific biomarkers, such as prostate-specific antigen (PSA) and alpha-fetoprotein (AFP)." (PMID 36530987, 2022). "Next, we evaluated the clinical significance of tumor VIPR1 and serum urea levels by measuring VIPR1 expression of HCC tissue, serum urea, and AFP level in a cohort of 43 HCC patients." (PMID 35864952, 2022). "Serum tumor markers, in particular, cancer antigen 125 (Ca 125), cancer antigen 19.9 (Ca 19.9), carcinoembryonic antigen (CEA), alphafetoprotein (AFP), human chorionic gonadotrophin (hCG), and lactate dehydrogenase (LDH) resulted in all normal ranges." (PMID 35659276, 2022). "In terms of serum tumor markers, the CEA, CA19-9, and AFP levels were similar between the two groups (P = 0.594, P = 0.785, P = 0.628, respectively)." (PMID 35296020, 2022). "At present, the most commonly used blood-based diagnostic markers for GAC in clinic usage are the universal tumor markers carcinoembryonic antigen (CEA), carcinoembryonic antigen (CA19-9, CA72-4, CA24-2, CA50, CA125), and alpha-fetoprotein (AFP)." (PMID 36505781, 2022). "In the 2-year RFS analysis, ALT, ALBI, AFP, PNI, APRI, MVI, number of tumours, tumour diameter, tumour capsule and PVTT were incorporated into the univariate and multivariate Cox regression equations." (PMID 35255845, 2022). "Comparative study on the available CP-based electrochemical biosensors for the detection of various cancer biomarkers (alpha-fetoprotein: AFP, carcinoembryonic antigen: CEA, circulating tumour cells: CTC; interleukin: IL)." (PMID 36671866, 2022). "VEGFR2-positive HCCs were confirmed by higher serum alpha-fetoprotein (AFP) levels, larger tumor dimensions (either on MRI or upon final pathology), and a higher LI-RADS score (all p < 0.001)." (PMID 36313714, 2022). "We incorporated the GGT, DB, AFP, PNI, NLR, SIRI, MVI, tumour diameter and PVTT into the univariate and multivariate Cox regression equations in the OS analysis." (PMID 35255845, 2022). "There were correlations between the maximum tumor diameter and stage of COG, time of postoperative AFP recovery, and survival (R = 0.452, −0.224 and −0.357, P < 0.05)." (PMID 36601033, 2022). "The combination of total tumour volume (TTV) below 115 cm3 and AFP below 400 ng/mL showed the predictive power of the post-transplant outcomes for candidates with HCC." (PMID 35740638, 2022). "The baseline clinical features we considered were pre‐treatment ALBI (Albumin‐Bilirubin) Grade, tumor size GTV, prior liver directed therapy, and pre‐treatment AFP (alpha‐fetoprotein)." (PMID 35343595, 2022). "In all LCT patients’ serum tumour markers (β-human chorionic gonadotropin - β-HCG, placental alkaline phosphatase - PLAP, alpha-fetoprotein - AFP, carcinoembryonic antigen - CA, ferritin, and lactate dehydrogenase - LDH) were negative." (PMID 36277728, 2022). "Except for the baseline AFP level, ATE/BEV and LENV showed comparable survival outcomes across baseline characteristics and tumor burden." (PMID 35406518, 2022). "TMCO1-AS1 expression was positively correlated with alpha-fetoprotein (AFP) level, vascular invasion, tumor stage, as well as tumor differentiation." (PMID 35141283, 2022).
tumor (continued). "Tumour characteristics, such as alpha-fetoprotein (AFP) concentration, tumour diameter, macrovascular invasion, and extended OLT criteria, are established risk factors for HCC recurrence." (PMID 35930293, 2022). "Tumor markers (human chorionic gonadotropin (HCG) and alpha fetoprotein (AFP)) in serum and cerebrospinal fluid (CSF) are useful for diagnosis, the evaluation of treatment response, and detecting recurrence after treatment." (PMID 35205726, 2022). "Sorafenib, an AFP level of ≥400 ng/mL, the presence of EHS, the presence of Vp4 (portal vein invasion in the main trunk), tumor size ≥5 cm, and age ≥65 years were poor prognostic factors in patients with major PVTT-HCC." (PMID 36230795, 2022). "Immunohistochemically, the tumor cells showed expression of SALL4 (sal-like protein 4), HNF1B (hepatocyte nuclear factor 1-beta), PAX8 (paired box gene 8), and α-FP (alpha fetoprotein)." (PMID 35204394, 2022). "Eleven variables were selected by lambda values corresponding to partial Likelihood Deviance in Lasso regression: ECOG PS, the combination of TACE, tumor number, PVTT, EHM, A/G, log (PLR), log (ALT), log (AFP), ALBI class and Child-Pugh score." (PMID 36532029, 2022). "Immunohistochemically, the tumor expressed glypican-3 (GPC3), SALL4, broad-spectrum keratins (AE1/AE3) and alpha-fetoprotein (AFP)." (PMID 35027045, 2022). "The results show that AFP and TBIL were important variables that simultaneously met both conditions in PVTT invasion, tumor number, treatment (TACE-A or TACE-AP), and albumin." (PMID 36249011, 2022). "Compared to inflammatory markers, tumor markers including CEA, AFP, HCG, and PSA generally showed better sensitivity for cancers." (PMID 35978826, 2022). "Although the isoforms of cord blood-derived normal AFP (nAFP) and HCC tumor-derived AFP (tAFP) only vary at one carbohydrate group, low amounts of tAFP, but not nAFP, markedly suppressed monocyte-derived DC differentiation." (PMID 35619702, 2022). "AFP-expressing DC-derived exosomes (DEXAFP) promote strong antigen-specific immune responses that inhibit tumor growth and reshap the tumor microenvironment." (PMID 35185900, 2022). "Compared with AFP, the expression rate of GPC-3 in early HCC is significantly higher, especially in patients with tumor diameters of less than 3 cm." (PMID 35624643, 2022). "Univariate Cox proportional hazards analysis showed that higher AFP levels, higher NLR, higher intrahepatic tumor number, presence of MVI and prior systemic therapy, and higher cfDNA levels were significantly associated with shorter PFS." (PMID 35884434, 2022). "Multivariate analysis showed that Child-Pugh score, CNLC stage, ascites, alpha fetoprotein (AFP), tumor size, and anti-HCV are related to OS." (PMID 37304009, 2022). "Tumor makers, such as carbohydrate antigen 19–9 (CA19-9), alpha-fetoprotein (AFP), carcinoembryonic antigen (CEA) and carbohydrate antigen 12–5 (CA12-5) were normal." (PMID 35534806, 2022). "Clinical and pathologic features, such as the tumor–node–metastasis (TNM) stage, alpha-fetoprotein (AFP) level, and abnormal thrombin, cannot provide an accurate evaluation of clinical outcomes in HCC patients." (PMID 36010950, 2022). "We did find that the ratio of CD8:OX40 was relevant to the AFP level, MVI-positive status, tumor number, and tumor diameter, which were identified as the risk factors for survival in another study." (PMID 35936682, 2022). "Sex (P=0.009), age (P=0.031), alpha-fetoprotein (P=0.005), HBV (P=0.046), postoperative treatment (P=0.003), postoperative surgery (P=0.041), tumor size (P=0.046) and MVI (P=0.005) were correlated with RFS." (PMID 35928871, 2022).
tumor (continued). "Alpha-fetoprotein (AFP), carbohydrate antigen 125 (CA125), carbohydrate antigen 19-9 (CA19-9), and carcinoembryonic antigen (CEA) are the most common tumor markers in clinical practice." (PMID 35874675, 2022). "A significantly high alpha-fetoprotein (AFP) level and a highly vascular tumor are often seen in patients with HCC." (PMID 36293521, 2022). "The classic prognostic model, tumor‐node‐metastasis (TNM) staging, as well as molecular biomarkers such as serum alpha-fetoprotein (AFP) levels, have been utilized for the diagnosis of HCC and for predicting its prognostic outcome to therapy." (PMID 36213826, 2022). "Alpha-fetoprotein (AFP) and protein induced by vitamin K absence or antagonist-II (PIVKA-II) are well-established tumor markers used for HCC evaluation." (PMID 35085305, 2022). "HBsAg: hepatitis B surface antigen; AFP: alpha-fetoprotein; TNM: tumor-node-metastasis; PVTT: portal vein tumor thrombus; OR: odds ratio; CI: confidence interval." (PMID 35186165, 2022). "Meanwhile, Extreme Gradient Boosting (XGBoost) was employed to combine four serum tumor-specific biomarkers (CEA, CA125, CA19-9, and AFP) to evaluate the performance of leveraging blood biomarker only." (PMID 37850180, 2022). "The levels of AFP, the stage of BCLC, status of Cirrhosis, tumor size, levels of MAP3K13, and levels of MAP3K15 were incorporated into a nomogram for a visual representation of OS." (PMID 35311629, 2022). "In HCC, antigens such as GPC3, AFP, and MUCIN are often upregulated in addition to some tumor stem cell antigens, which are the targets that CAR-T cells are often designed to attack." (PMID 36291802, 2022). "Liver tumour markers, such as AFP, GSTp2, and GPC3, in GKO tumours were reduced in comparison to WT tumours." (PMID 35867177, 2022). "Univariate analysis revealed that age (p = 0.039), AFP (p = 0.008), GGT (p = 0.024), tumor number (p = 0.004), MVI (p = 0.001), and differentiation (p = 0.048) were associated with RFS." (PMID 34745962, 2021). "Multivariate analyses for OS were performed using the data before and after PSM with the following items: treatment group; sex; age; etiology; tumor size; MVI, severe MVI, and EHS presence; C-P class; AFP; and DCP." (PMID 33562793, 2021). "In this study, 6 of all 7 risk factors associated with early-relapse were tumor-related factors, including preoperative blood AFP level, MVI classification, number of tumors, largest tumor diameter, the status of serosal invasion and satellite nodules." (PMID 34229698, 2021). "Higher serum concentration of AFP and VEGF-A, lower lymphocyte count, peritumoral enhancement, irregular tumor shape, and intratumoral artery were identified as significant predictors for MVI." (PMID 35004273, 2021). "In this project, we identified protein expression in situ using AFP-negative HCC tissue [AFP(−)-HCC] and adjacent non-tumor liver tissue (control group, CK)." (PMID 34722278, 2021). "Tumor markers (including NSE, AFP, CEA, CA199) were examined in 11 cases; NSE increased in 4 children, and AFP increased in 1 patient." (PMID 34307241, 2021). "For the Ontario criteria, patients were eligible based on total tumor volume (TTV) measured less than 145 cm3 and AFP is less than 1000 ng/mL." (PMID 34638395, 2021). "These AUC values were even better than those obtained by the routine tumor markers CEA, CA19-9, and AFP (AUC values of 0.689, 0.687, and 0.634, respectively)." (PMID 35008366, 2021).
tumor (continued). "With higher RECK levels identified in tumors, patients had better survival, lower AFP level, low incidence of HBV infection and vascular invasion, and tumors demonstrated better tumor differentiation." (PMID 34093791, 2021). "Circulatory tumor markers including carcinoembryonic antigen (CEA) for CRLM, α-fetoprotein (AFP) for HCC, and carbohydrate antigen 19-9 (CA19-9) for PDAC and CCA were not elevated in 5/27 patients." (PMID 34155211, 2021). "Studies have shown that patients with AFP-NHCC often have special clinicopathologic characteristics and prognosis, they have higher tumor differentiation, earlier TNM staging, smaller tumor size, and higher survival rates." (PMID 33685417, 2021). "The RETREAT score showed elevated AFP, the presence of MVI on the explant, and the largest viable tumor diameter plus the number of viable tumors on the explant as possible prognostic factors." (PMID 34885087, 2021). "The current study has demonstrated that NLR alone gave an AUROC of 0.728, higher than AFP, CEA or tumor size alone." (PMID 34834430, 2021). "The serum tumor markers beta subunit of human chorionic gonadotropin (HCG) and alpha-fetoprotein (AFP) are used for diagnosis, monitoring of treatment efficacy, and follow-up procedures." (PMID 33683412, 2021). "High numbers of PD-1 positive intra-tumor lymphocytes, CIK cell cytotoxicity and serum AFP were suggested to serve as prognostic factors to predict clinical outcomes related to CIK as an adjuvant therapy." (PMID 34696292, 2021). "Second, tumor markers (CEA, SCC, AFP, etc.)and other potentially valuable hematological indicators were not included in this study." (PMID 34294070, 2021). "Higher serum concentrations of AFP and VEGF-A, lower lymphocyte count, peritumoral enhancement, irregular tumor shape, and intratumoral artery were identified as significant predictors for MVI." (PMID 35004273, 2021). "Serum tumor markers including AFU, AFP, CEA, CA199, CA125 and CA724, are of great importance in the diagnosis, prognostic prediction and recurrence monitoring of gastrointestinal malignancies." (PMID 33402124, 2021). "Of the 52 patients with specific information on testicular tumor markers, lactate dehydrogenase (LDH) was elevated in 3/52 cases (6%), human chorionic gonadotropin (HCG) in 2/52 cases (4%), and alpha-fetoprotein (AFP) in 1/52 cases (2%)." (PMID 33559739, 2021). "The patients in NsA group had lower levels of ALB (p = 0.022), higher levels of AFP (p = 0.034), higher levels of AST (p < 0.001), longer PT (p = 0.0025), and larger tumor size (p < 0.001) compared with NtA group." (PMID 34643050, 2021). "CCT5 mRNA was significantly overexpressed in HCC patients with alpha-fetoprotein (AFP) > 300 ng/ml, BCLC staging B-C, TNM staging III and main tumor size > 5 cm (all P < 0.05)." (PMID 34522182, 2021). "The other tumor markers such as carbohydrate antigen 19-9 (CA19-9), carcinoembryonic antigen (CEA), and alpha-fetoprotein (AFP) were within normal range." (PMID 34340706, 2021). "Among them, AFP remains a primary molecular biomarker for HCC diagnosis and prognosis recognized as a “golden standard” among serum tumor markers." (PMID 33562077, 2021). "Significance was found for all 4 clinical tumor characteristics of maximum tumor diameter (MTD), tumor number, macroscopic portal vein thrombosis (PVT) and serum alpha-fetoprotein (AFP) levels, as expected." (PMID 34540270, 2021). "The combination of α-fetoprotein (AFP) levels with auto-antibody titers against 10 antigens increased the sensitivity for detecting stage 1 HCC by 40.00% and stage 2 by 55.00% over the tumor antigens auto-antibodies panel alone or AFP alone." (PMID 33672007, 2021). "Intratumoral medication of AFP-CAR-T was reported to lyse HCC cells via cytokine dependent manner and suppress tumor growth in mouse model." (PMID 34372912, 2021).